INS (insulin)
Diseases named in the same sentence as INS in open-access papers (continued):
Sharing a sentence is not in itself a finding about the gene and the disease.
Obesity (continued). "Body mass index (BMI), SAT and VAT (both raw volumes and corrected indexes) were higher in subjects with obesity, in parallel with decreased glucose-infusion rate during the euglycemic clamp as an indicator of decreased insulin sensitivity." (PMID 36902180, 2023). "Flies fed a high-sugar (HS) diet exhibit a reduced lifespan and healthspan, including obesity, hyperglycemia, and impaired immunity, reproduction, feeding behavior, insulin signaling, and cardiac function." (PMID 37398379, 2023). "Growing experimental evidence suggests that TRPA1 plays an important role in weight gain, obesity, and insulin secretion." (PMID 36971291, 2023). "For example, a study has shown that in mice, a high-fat diet led to obesity, systemic insulin resistance, dysregulated lipid metabolism, and depressive-like behavior." (PMID 36982361, 2023). "Obesity is endocrinologically responsible for the physiological consequences of less insulin sensitivity followed by hyperinsulinemia, glucose intolerance, proinflammation, hepatic steatosis, dyslipidemia, tumorigenicity, and metastasis." (PMID 37629569, 2023). "The changes in brain volume are mainly due to the impaired insulin transport to the brain that often arises in the case of obesity." (PMID 37237937, 2023). "The highest AUCROC values identifying obesity were found for insulin, C-peptide, leptin and HOMA-IR values." (PMID 37373485, 2023). "mTOR activation with the pathways of p70S6K and 4EBP1 can promote insulin secretion in pancreatic β-cells and increase resistance to β-cell streptozotocin toxicity and obesity in mice." (PMID 37238686, 2023). "Acute SIT can reduce glucose and insulin levels in postprandial states in healthy participants, in people with overweight and obesity, and in patients with metabolic disorders." (PMID 36695728, 2023). "For instance, within an HNF-4α/MODY1 pedigree, obesity was observed in two diabetic members, one being a 7-year-old with fasting plasma glucose of 203 mg/dL and fasting insulin of 27 μU/mL." (PMID 38333726, 2023). "Previous studies with regular exercise for participants with overweight and obesity have shown improvements in AUC insulin." (PMID 36760521, 2023). "These cytokines are considered pro-inflammatory markers of obesity and can alter the insulin signaling pathway, resulting in reduced glucose uptake and increased serum glucose levels." (PMID 37569390, 2023). "Gut dysbiosis promotes weight gain and obesity by inducing an inflammatory response, reducing fat and cholesterol metabolism, and decreasing insulin sensitivity." (PMID 37249983, 2023). "This was first confirmed from knockout animal models that displayed elevated insulin levels and reduced insulin sensitivity in addition to the hyperphagia and obesity." (PMID 36984824, 2023). "For example, anti-obesity drugs can be anti-diabetic to some extent, and some anti-diabetic medicines, in contrast, have been shown to increase body weight, such as insulin." (PMID 37152942, 2023). "Generally, the assisted pharmacological treatment of PCOS includes combined oral contraceptive pills (COCPs), insulin-sensitizing agents, anti-androgen and anti-obesity pharmacological agents." (PMID 37525285, 2023). "These mice also show lower glucose levels and higher insulin sensitivity, as well as resistance to general obesity." (PMID 37298278, 2023). "Increased adipokine production in obesity affects various functions, including appetite and energy balance, insulin sensitivity, blood pressure, immunity, angiogenesis, hemostasis, and lipid metabolism, all of which are also linked to cardiovascular diseases." (PMID 37359050, 2023). "Obesity also reduces the concentration of adipokines, which have a positive effect on increasing insulin sensitivity." (PMID 37371961, 2023).
Obesity (continued). "Experimental studies conducted in a mice model of NAFLD demonstrated that chronic administration of monacolin K reduced circulating insulin levels, obesity-related inflammatory markers and liver fat deposits, thus slowing progression of NAFLD to NASH." (PMID 37111106, 2023). "Obesity-mediated insulin metabolism regulation involves several complex pathways, such as inflammatory pathways, mitochondrial dysfunction, gut microbial dysregulation, and fatty extracellular matrix remodeling." (PMID 37537674, 2023). "In summary, WWP1 participates in obesity‐related metabolic dysfunction and pathologies related to hepatic steatosis via suppressed insulin signaling." (PMID 37032433, 2023). "Obesity can be characterized as polygenic or ‘common obesity’ in 95% of cases, involving multiple genes that control thermogenesis, energy homeostasis, neurohormonal signalling and leptin-insulin interactions." (PMID 37233716, 2023). "In conclusion, FGF21 analogs must be tested in new clinical trials, as they appear to exhibit great potential for treating signs of Metabolic Syndrome such as high blood insulin, obesity, and especially hypercholesterolemia." (PMID 37948566, 2023). "The activity of FAS can be improved by insulin in adipocytes and high FAS expression significantly increased diacylglycerol deposition and caused obesity." (PMID 36766716, 2023). "ACC2 knockout mice resist obesity and retain insulin sensitivity in a high-fat diet-induced diabetes model." (PMID 37233656, 2023). "Despite its wide usage, it fails to reconstitute the main pathological processes of NAFLD specific to humans including obesity and expressed peripheral resistance to insulin." (PMID 38434194, 2023). "Yet, in conditions such as obesity and metabolic syndrome, insulin‐mediated sympathetic activation is diminished, implying that other factors beyond insulin contribute to elevated sympathetic activity in obese individuals." (PMID 37642329, 2023). "Many of these molecules are increased in obesity, affecting insulin sensitivity through various mechanisms." (PMID 38138997, 2023). "Overall, both NPY and acyl ghrelin levels are increased in patients with obesity and T2D, contributing to adiposity and reduced insulin sensitivity, whereas dopamine action is dependent on subtype receptors." (PMID 36904281, 2023). "We showed that deletion of GADD45A significantly increases Ucp1 expression and induces iWAT browning, protects mice from HFD-induced obesity, and improves glucose tolerance and insulin sensitivity." (PMID 37807064, 2023). "Alleviate obesity and hepatic steatosis; improve insulin pathway, hepatic glycogen synthesis, and glucose homeostasis; upregulate energy metabolism; increase acetic acid and taurine." (PMID 38068759, 2023). "The need for intensifying insulin regimens depends, at least in part, on a progressive decline in insulin sensitivity, which, in turn, is related to several factors, including obesity and chronic insulin exposure per se." (PMID 38201893, 2023). "Recent experimental studies demonstrate that manipulation of DNA methylation enzymes in adipocytes can induce or prevent obesity and T2D, through cellular effects on energy expenditure and insulin sensitivity." (PMID 37188674, 2023). "Central and peripheral insulin signaling are both necessary for normal nutrient handling and disruption of either signaling pathway results in hyperinsulinemia, hyperphagia and obesity." (PMID 37546289, 2023). "The inhibition of basal insulin hypersecretion due to obesity and the inhibition of glucose-stimulated insulin secretion were identified after the direct in vitro administration of rimonabant in islets." (PMID 37371762, 2023). "Inflammation acts as a potential link between obesity and impaired insulin sensitivity based on the release of inflammatory mediators by adipose tissue." (PMID 37568405, 2023).
Obesity (continued). "In this study, we further demonstrated its therapeutic potential to reduce obesity-induced hepatic steatosis and liver injury, improve insulin sensitivity, and reverse hypertriglyceridemia." (PMID 36442615, 2023). "Free rimonabant treatment resulted in both improved obesity-induced glucose intolerance, and improved insulin sensitivity." (PMID 36442615, 2023). "In obesity, there are observed higher levels of resistin, contributing to impaired insulin signaling and increased inflammation, which can further worsen metabolic dysfunction." (PMID 37629396, 2023). "For example, the IS-Matsuda Index as an index of insulin sensitivity is already impaired in more than half of 6-year-old children with obesity, which shows that potential metabolic dysfunction can occur very early in life." (PMID 36534178, 2023). "Women with PCOS are more likely to have problems with insulin resistance, which can lead to high levels of insulin in the blood and other metabolic issues such as high cholesterol, type 2 diabetes, and obesity." (PMID 37432488, 2023). "The increased insulin : GH ratio stimulates energy storage and lipid synthesis and inhibits lipid breakdown and thereby promotes obesity by promoting higher fat accumulation and lower energy expenditure." (PMID 36901984, 2023). "Studies also have shown that autophagy haploinsufficiency with deletion of the Atg7 gene in mouse models of obesity leads to increased insulin resistance with elevated lipids and inflammation." (PMID 37238686, 2023). "Adipose-specific deletion of Lexis counteracted diet-induced obesity, improved insulin sensitivity, and enhanced energy expenditure." (PMID 37909330, 2023). "In more detail, in obesity, adipose tissue is dysfunctional and lacks the ability to store excess energy, leading to increased lipolysis and insulin resistance." (PMID 37834153, 2023). "Pathway analysis showed that some of our DE lncRNAs and their partner genes are primarily involved in glucose and lipid metabolism and in insulin-related pathways, essential in regulating adipogenesis and obesity." (PMID 36735680, 2023). "The biological mechanism of obesity-related kidney failure includes hemodynamic changes, adipose tissue increases, and insulin resistance pathways." (PMID 37047953, 2023). "SCFAs maintain immune balance and not only play an important role in maintaining intestinal function but impact insulin secretion and reduce obesity." (PMID 37841402, 2023). "AMPK is well known as a master metabolic switch, and its activity correlates well with improving obesity and insulin sensitivity by regulating mitochondrial function and fatty acid metabolism in skeletal muscle." (PMID 37143096, 2023). "Exposure to maternal diabetes and/or obesity in utero is likely to influence offspring body composition, insulin sensitivity and beta cell function." (PMID 37442824, 2023). "BMP4 is increased in patients with metabolic disorders such as DM, obesity, and nonalcoholic fatty liver disease(NAFLD), and its level is negatively associated with insulin sensitivity." (PMID 37370018, 2023). "Accordingly, in this review, we will summarize the latest findings concerned with the metabolic contribution of obesity in OA pathogenesis, with particular emphasis on dyslipidemia, insulin resistance and adipokines." (PMID 37180899, 2023). "Prediabetes in obesity is driven by hyperinsulinemia and overworking of the pancreas while poor β-cell function and poor insulin secretion are major drivers in the undernourished group." (PMID 37601212, 2023). "This is consistent with work our group has conducted showing that EVs are decreased in relation to circulating post‐prandial insulin levels as well as AIx75 following an oral glucose tolerance test (OGTT) in individuals with obesity and prediabetes." (PMID 36597186, 2023). "IR induced by obesity is characterised by impaired insulin function, as the adipose tissue induces systemic IR." (PMID 37795371, 2023).
Obesity (continued). "Regardless of sex, lean subjects on low atherogenic risk displayed worsening trends across the AIP quartiles in proxy measures of obesity, insulin sensitivity, continuous MetS score, and leukocyte counts." (PMID 37508640, 2023). "Assuming the insulin sensitivity function also depends on the obesity-related factor X can overcome this limitation." (PMID 36848379, 2023). "The efficacy of CGA in addressing obesity, reducing fasting plasma glucose and enhancing insulin sensitivity was also well-documented." (PMID 38390397, 2023). "The findings discussed in the present review suggest that moderate exercise is capable of improving hypothalamic inflammation in obesity, restoring leptin and insulin sensitivity, and exerting positive effects on food intake and body weight." (PMID 36829858, 2023). "Individuals with the classic Laron syndrome present with short stature, obesity, low blood sugar, and congenital IGF-I deficiency (with low serum IGF-I) with decreased insulin/IGF-I signaling activity despite elevated basal serum GH." (PMID 36901984, 2023). "An ultra-processed high palatable diet (HP), also named the cafeteria diet, or Western-style diet, is enriched in simple sugars and saturated fat, and its consumption contributes to weight gain, obesity, and insulin resistance." (PMID 36984825, 2023). "For instance, obesity can upregulate CaMKII activity via enhancing ER stress, which further compromises the insulin signaling in the liver." (PMID 37303813, 2023). "Insulin resistance is the hallmark of obesity and T2DM and is the core of pathophysiological characteristics of insulin-sensitive tissues, including skeletal muscle (SKM)." (PMID 37627494, 2023). "YLTB ameliorates the host features of PCOS including glucose tolerance, insulin insensitivity, lipid metabolic disorder, and obesity." (PMID 36814581, 2023). "Whole-body heterozygous deletion of the Pik3r1 regulatory subunits (Pik3r1+/−), but not knockout of Pik3r2, preserves whole-body WAT and skeletal muscle insulin sensitivity, despite severe obesity." (PMID 37628845, 2023). "Obesity is usually characterized by increased levels of fasting plasma insulin and abnormally elevated insulin response to an oral glucose load." (PMID 37103396, 2023). "In the current study, dulaglutide, a long-acting GLP-1 agonist, exhibited potential therapeutic benefits for MS-induced T2DM and obesity by direct insulin-dependent effects that improve hyperglycemia and IR." (PMID 36991247, 2023). "Constitutive activation of systemic insulin release from Drosophila Insulin-producing cells (IPCs) mimics the effect of diet-induced obesity on glial draper expression." (PMID 36945507, 2023). "Leptin, the 167 amino acid product of the human gene for obesity, is involved in glucose and insulin signaling pathways through various mechanisms." (PMID 37375800, 2023). "Obesity also increases insulin and insulin-like growth factor and obesity-related regulatory proteins." (PMID 37305586, 2023). "In obesity, stress, hormones (insulin, catecholamines, glucocorticoids), hypoxia, and inflammation interact and affect IL6 production." (PMID 36986146, 2023). "For example, B. acidifaciens can prevent obesity and improve insulin sensitivity in mice, and B. thetaiotaomicron can reduce plasma glutamate concentration and alleviate diet-induced body-weight gain and adiposity in mice." (PMID 37928663, 2023). "In human myotubes from a donor with obesity, vaspin had a significant effect on insulin-stimulated glucose uptake." (PMID 37152954, 2023). "Perturbation of MC4R signaling in the PVH alone, or in both PVH and DMV results in hyperphagic obesity with reduced energy expenditure and defects in insulin sensitivity." (PMID 37443835, 2023). "Lipid and glucose metabolism and insulin sensitivity are strongly affected by obesity and overweight conditions." (PMID 37049562, 2023).
Obesity (continued). "In conditions, including obesity and Alzheimer’s disease (AD), where there is a dysfunction in brain insulin action, known as insulin resistance, insulin BBB transport is also impaired." (PMID 37076875, 2023). "Obesity is associated with inflammatory changes in WAT that lead to IR, which is the inability to sense insulin and uptake blood glucose and other nutrients." (PMID 36175539, 2023). "Importantly, PIPs play key roles in the PI3K/AKT insulin signaling pathway and glucose and lipid metabolism; dysregulation of these signaling pathways is associated with various metabolic diseases, including diabetes, obesity, inflammatory conditions, and cardiovascular disease." (PMID 37524877, 2023). "After long-term physical exercise, irisin was demonstrated to improve glucose homeostasis, which was correlated with better glucose regulation, less insulin resistance, and consequently obesity." (PMID 36843614, 2023). "Important dietary flavonoids with anti-obesity and/or insulin-sensitizing effects that impact oxidative stress and macronutrient metabolism." (PMID 37252233, 2023). "In mice with modest obesity brought on by a high-fat diet, ghrelin deprivation increased insulin release and prevented decreased glucose tolerance." (PMID 36936164, 2023). "Described as anti-obesity and anti-diabetic, FGF-21 and its receptor agonists improve insulin sensitivity (IS) and promote weight loss by stimulating brown fat thermogenesis and increasing release of adiponectin serum levels." (PMID 37239098, 2023). "The present review addresses the possible role of SRH in the habitual ingestion of sugary snacks in people with obesity or overweight, taking glucose effectiveness (Sg), an insulin-independent mechanism of blood glucose disposal, into account." (PMID 37367911, 2023). "Obesity is usually related to elevated insulin levels in the blood, with enhanced ovarian androgen production as a result." (PMID 38111393, 2023). "ER stress caused by obesity stimulates JNK activation, which acts as a core mediator resulting in modifications in insulin signaling." (PMID 38140341, 2023). "Age, sex, obesity, HbA1c level, insulin use, GFR, and presence of diabetic retinopathy and cardiovascular disease did not significantly affect antibody levels." (PMID 37479776, 2023). "Obesity is a metabolic condition characterized by high insulin levels, high cholesterol levels, high leptin levels, and chronic inflammation." (PMID 38111393, 2023). "LPS is secreted by abundances of Parabacteroides, Lachnoclostridium, Lachnospiraceae NK4A136 group and Romboutsia, triggering proinflammatory cytokines, obesity, and insulin resistance." (PMID 37377484, 2023). "The increase in the IL-6 level induced by obesity decreases insulin sensitivity in the liver, muscles, pancreas, and white adipose tissue (WAT)." (PMID 37371961, 2023). "Compared to that in lean insulin-sensitive patients, the circulation of 65 and 73 miRNAs increased and decreased, respectively, in patients with obesity-mediated IR (374 miRNAs detected in total)." (PMID 37537674, 2023). "Skeletal muscle inflammation is a driver of insulin resistance, and exercise is an effective countermeasure to mitigate skeletal muscle inflammation and insulin resistance in the context of obesity." (PMID 37675469, 2023). "Obesity and its common comorbidities are also characterized by profound disturbances in insulin homeostasis and related biological processes, such as carbohydrate and lipid metabolisms." (PMID 37672200, 2023). "Several risk factors associated with BC development have been described comprising molecular alterations, obesity, glucose metabolism, and others involvement, also, the Insulin (Ins)/Insulin-like growth factor (IGF) system." (PMID 37361518, 2023). "It was shown that the ROC curve for insulin lies below the ROC curve for leptin, and thus leptin was the indicator with the highest discriminant value for obesity." (PMID 37373485, 2023).